AR (androgen receptor)
Diseases named in the same sentence as AR in open-access papers (continued):
Sharing a sentence is not in itself a finding about the gene and the disease.
prostate carcinoma (continued). "Androgens and androgen receptor (AR) are known to be important drivers of prostate cancer progression." (PMID 29269934, 2017). "Nuclear AR protein is detected in secondary prostate cancer tumors from patients failing androgen deprivation therapy." (PMID 28306720, 2017). "In prostate cancer, plenty of LncRNAs, including PCGEM1, SOCS2-AS1, PlncRNA-1, CTBP1-AS, DRAIC and PCAT29, have been reported to be associated with AR pathway, and thus act as regulators in the development of PCa." (PMID 28771526, 2017). "Expression levels of the splicing regulator Sam68 protein also increase in prostate cancer and can drive AR CE3 splicing inclusion." (PMID 28382513, 2017). "Here we show that Enoyl-CoA delta isomerase 2 (ECI2) is a novel AR-target that promotes prostate cancer cell survival." (PMID 28415728, 2017). "In the 1940s Charles Huggins reported remarkable palliative benefits following surgical castration in men with advanced prostate cancer, and since then the androgen receptor (AR) has remained the main therapeutic target in this disease." (PMID 28085048, 2017). "We re-analyzed AR ChIP-seq data from human tissue samples, and putative AR-binding site in castration-resistant prostate cancer patient samples was found inside the ECI2 gene body (chromosome coordinates in Human Genome 18: chr6:4,075,826-4,076,114)." (PMID 28415728, 2017). "A liquid biopsy analysis including this predictive AR modification from circulating prostate cancer cells has since been established." (PMID 28380417, 2017). "Androgen receptor (AR) can mediate the transcription of genes involved in prostate cancer cell proliferation and survival." (PMID 29228644, 2017). "In this study, we found that either NRIP or the AR was highly expressed in human prostate cancer tissues." (PMID 28212551, 2017). "(PubMed ID: 18593950)” and “AR remains important in the development and progression of prostate cancer." (PMID 29029598, 2017). "SGK1 is known to be up-regulated after androgen receptor activation in prostate cancer and plays an important role in androgen receptor dependent tumor proliferation and survival." (PMID 28336914, 2017). "On the other hand, activation of AR reduces PPARγ levels and activity within human prostate cancers." (PMID 29181019, 2017). "Expression of CDK6 markedly enhanced activation of the luciferase reporter in the presence of the AR in PC3 human prostate cancer cells." (PMID 28262798, 2017). "Prostate cancer progression is controlled by the androgen receptor and new blood vessel formation, or angiogenesis, which promotes metastatic prostate cancer growth." (PMID 28394264, 2017). "Because androgen and androgen receptor signaling promotes prostate cancer progression, the standard treatment for patients with advanced prostate cancer employs androgen-deprivation therapy (ADT)." (PMID 29017493, 2017). "Site directed mutagenesis of Ser-578 on the AR in castrate-resistant prostate cancer cell lines demonstrated that PKC-dependent phosphorylation was reduced on average by 50% when compared to wild type cells." (PMID 27902483, 2017). "The most successful prostate cancer prevention strategies to date have focused on inhibition of the androgen receptor (AR) via blockade of dihydrotestosterone (DHT) production using 5α-reductase inhibitors." (PMID 28099154, 2017). "As a result, drugs that target the AR signaling pathway are routinely used to treat patients with advanced forms of prostate cancer." (PMID 29181019, 2017). "To examine the relationship between CREB3L4 and AR, with regard to prostate cancer cell proliferation, we performed reporter assays using a PSA gene promoter construct." (PMID 28338058, 2017). "Previous studies revealed that PIAS1 is regulated by AR, and its expression is increased in prostate cancer." (PMID 29214142, 2017).
prostate carcinoma (continued). "These two candidates, LHJ-647 and HWC-489, additionally suppressed prostate cancer cell xenografts harboring endogenous AR and growth in a NOD/SCID mouse model with statistical significance, based on comparisons of tumor volume, tumor weight." (PMID 29050220, 2017). "Recently, it has been demonstrated that the stability of the androgen receptor in prostate cancer cells is regulated by the de-ubiquitinase USP7, also known as herpesvirus-associated ubiquitin-specific protease." (PMID 28415632, 2017). "In prostate cancers, the ability of PPARγ to regulate AR function varies depending on the ability of tumors to respond to castration." (PMID 29181019, 2017). "Androgen receptor (AR) signaling has a critical role in the development and progression of prostate cancer." (PMID 28261196, 2017). "We analyzed the function of AR-responsive miRNAs in prostate cancer cells and proposed a novel working model that androgen-induced miRNAs functions as “epigenetic modifiers” and regulate the global epigenetic condition for progression to HRPCs/CRPCs." (PMID 28783103, 2017). "Regardless, the evidence collectively supports stromal AR signalling acting to induce prostate cancer cell proliferation and potentially play an important role in early prostate carcinogenesis." (PMID 28117763, 2017). "Increasing FOXA1 activity causes indiscriminate opening of closed chromatin, attracting the AR to ARE half sites at the expense of genes with canonical ARE that promote prostate cancer progression." (PMID 28264478, 2017). "As prostate cancers progress to hormone refractory metastatic disease, usually under conditions of androgen deprivation or complete androgen blockade, the epithelial AR is widely believed to have acquired the capacity to drive tumour growth." (PMID 28117763, 2017). "Together, these data identify ING3 as a proto-oncogene in PC by regulating the AR pathway through acetylation, and identify it as a novel prognostic biomarker for primary prostate cancer." (PMID 28511652, 2017). "The initiation and progression of prostate cancer is uniquely dependent on androgen receptor (AR)-induced signaling." (PMID 28077787, 2017). "Consistent with the results of liver developmental studies, one member of the FoxA family, FOXA1, works as a pioneer factor in the AR and estrogen receptor (ER) pathways in prostate cancer and breast cancer cells." (PMID 28264478, 2017). "The androgen receptor (AR) pathway is a major contributor to prostate cancer and, coupled with other oncogenic signaling pathways, plays a key role in the initiation and progression of this disease." (PMID 28511652, 2017). "Targeting the pioneer factor FOXA1 showed contradictory results for AR activity and prostate cancer prognosis." (PMID 28264478, 2017). "While AR can be targeted in castration-resistant prostate cancer with ADT or anti-androgens, glucocorticoids can be used to relieve pain or suppress androgens." (PMID 28168446, 2017). "While our study confirms the significant association with AR, the diagnostic value of HOBX13 appears less convincing, as only 60.4% of prostate cancer metastases were positively stained." (PMID 28555048, 2017). "Although targeting of AR has been used in prostate cancer therapy, very less information is available on the therapy against breast cancer and its prognosis." (PMID 29254284, 2017). "Perhaps significantly, in men of African descent where there is a higher incidence of prostate cancer compared to Caucasian men, there is reportedly higher stromal AR expression." (PMID 28117763, 2017). "We have previously found that AURKA is upregulated in prostate cancer cells that overexpress AR (VCaP and LNCaP cells stable-transfected with AR) under DHT stimulation and is overexpressed in CRPC18,19." (PMID 29269934, 2017). "Prostate cancer cells often utilize lipids derived from androgens through the expression of an androgen receptor." (PMID 28674679, 2017).
prostate carcinoma (continued). "Aberrant Src activity is detected in malignant prostate cells and present in several AR-positive prostate cancer cell line models exhibiting androgen-independent growth." (PMID 28144231, 2017). "Androgen receptor (AR) signalling pathway dominates the survival, proliferation and growth of prostate cancer." (PMID 28151478, 2017). "We now understand that the beneficial effects of castrating therapy are a direct result of inhibiting AR-signaling, and as such targeting the AR has remained the backbone of prostate cancer therapy since the 1940s." (PMID 28085048, 2017). "ECI2 was identified as a putative AR target gene in castration-resistant prostate cancer tissue samples using ChIP-seq technology." (PMID 28415728, 2017). "An early study showed that IL-8 promoted androgen-independent proliferation of prostate cancer cells via inducing androgen receptor expression and activation." (PMID 28423553, 2017). "In this respect, it has been suggested that 14-3-3 interaction with AR promotes the transcriptional activation of PSA promoter in prostate cancer cells." (PMID 28915724, 2017). "Since ECI2 was over-expressed in prostate cancer patient samples, we moved on to assess AR-dependent regulation of this gene." (PMID 28415728, 2017). "They noted that forkhead factor binding motif FOXA1, was highly expressed in HER2 and AR-positive breast tumors, which is similar to AR-positive prostate cancers and seems to be involved in recruitment of ER and AR to their transcription regulatory elements." (PMID 28245550, 2017). "PRNCR1 also known as PCAT8, was highly expressed in prostate cancer, and can mediate the prostate cancer cells gene activation programs and proliferation by binding to the androgen receptor." (PMID 28159929, 2017). "Androgen receptor (AR) is a key transcription factor playing a critical role in prostate cancer (PCa) initiation and progression." (PMID 28881808, 2017). "Another study showed that the increased cytosolic β-catenin was degraded due to the effect decursin inhibition of AR-independent prostate cancer." (PMID 29215592, 2017). "Together, these results indicated that with subsequent loss of ID4, Hsp27 and FKBP52 promote nuclear translocation and transcriptional activity of AR, followed by increased cell proliferation in prostate cancer L(−)ID4 cell lines." (PMID 28252832, 2017). "Increased expression of AR cofactor/coregulator proteins as well as ligand-independent activation of AR via growth factors and cytokines can also enhance AR signaling within castration-resistant prostate cancer cells." (PMID 29181019, 2017). "Various functional studies, including our own work, have elucidated the complicated influence that AR collaborators have on prostate cancer progression." (PMID 28264478, 2017). "Together with its expression of wild-type PTEN and AR, 22Rv1 provided another good model for castration resistant prostate cancer." (PMID 28350865, 2017). "This suggests that any reduction in AR signaling would increase the amount of functional PPARγ and enhance the antitumor effects of PPARγ within prostate cancers." (PMID 29181019, 2017). "Here, we report that AR expression increased in prostate cancer tissues and support the proposed model of the AR as an oncogene in cancer." (PMID 28212551, 2017). "AR contributes to several kinds of human cancer, including prostate cancer, urothelial carcinoma, and especially HCC." (PMID 29312607, 2017). "In summary, via demonstrating the role of USP14 in AR stabilization in androgen-responsive prostate cancer, here we provide a potentially new strategy for inhibiting AR-mediated prostate cancer carcinogenesis or progression through inhibition of USP14." (PMID 28151478, 2017). "Thereof, we further compared the expression levels of NRIP and AR in prostate cancer tissues analyzed by immunohistochemistry." (PMID 28212551, 2017).
prostate carcinoma (continued). "Studies have demonstrated that persistent AR signalling remains the key driver in the progression to CRPC, and AR down-regulation is considered a preventive strategy for prostate cancer." (PMID 28444639, 2017). "Other studies have shown that GAK is a transcriptional coactivator of the androgen receptor (AR), a ligand-dependent transcription factor highly expressed in prostate cancer." (PMID 28472763, 2017). "While AR continues to be expressed in many advanced prostate cancers, AR expression is lost in stromal cells during the process of tumor progression and the development of metastatic tumors." (PMID 29181019, 2017). "Previous research conducted in prostate cancer showed that AR positively regulated mTOR activity and compensatory increase of AR function due to a repressed mTOR signal is advantageous for tumor cell survival." (PMID 28060723, 2017). "Regarding to hormonal imbalance, 5α-dihydrotestosterone (DHT), androgen receptor (AR), female hormones estrogens are critical targets for prostate cancer chemopreventions." (PMID 28415774, 2017). "Activation of AR induces Klk4 transcription in prostate cancer cells, while activation of PR does so in breast cancer cells." (PMID 29249975, 2017). "Androgen signaling controls the growth of prostate gland and AR plays important roles throughout the various stages of prostate cancer." (PMID 28400729, 2017). "In conclusion, our findings here support that the AR NTD is a feasible therapeutic target for the development of novel drugs for the treatment of prostate cancer." (PMID 28306720, 2017). "It is possible that AR uses at least two different strategies to control metabolism in prostate cancers cells: the direct regulation of AR target genes and modulation of PPARγ function." (PMID 29181019, 2017). "It is worth noting that melatonin, which acts by inhibiting both activated AR and NF-κB signaling in prostate cancer cells, has been demonstrated to be a novel prostate growth inhibitor." (PMID 28561752, 2017). "The role of androgen receptor (AR) in castration therapy-resistant prostate cancer is a subject of intensive investigation in urological oncology." (PMID 29214142, 2017). "Prior work has suggested that GR can attenuate AR signaling and inhibit growth in AR-positive prostate cancer models, raising the possibility that tumor cells gain a growth advantage upon GR silencing." (PMID 28891793, 2017). "Androgen receptor (AR) is a member of the steroid receptor family and a therapeutic target for all stages of prostate cancer." (PMID 28306720, 2017). "AR plays a pivotal role in prostate cancer by transactivation of multiple genes involved in tumorigenesis." (PMID 28415774, 2017). "(A) Lysates from three AR-positive prostate cancer cell lines were subject to western blotting with antibodies against ING3, GAPDH, and actin." (PMID 28511652, 2017). "We set out to analyse how the PHB modulated the cell cycle and how its activity is regulated by AR in prostate cancer cells." (PMID 28504694, 2017). "This has previously been observed in prostate cancer, where DHT treatment and AR activation was associated with decreased local inflammation, inflammatory growth factor production and T-lymphocyte proliferation." (PMID 28415597, 2017). "Further, sequencing of these CK-/AR+ CTCs revealed frequent AR gene amplifications as well as other alterations that are consistent with prostate cancer." (PMID 28957377, 2017). "Over the last decade, sophisticated technologies for investigating transcriptional networks have broadened our understanding of AR signaling in prostate cancer." (PMID 28264478, 2017). "We conclude that in normal prostate cells RNase L is a negative regulator of AR signaling and loss of RNase L function in HPC can enhance AR signaling which is a hallmark of most prostate cancers." (PMID 28257035, 2017).
prostate carcinoma (continued). "AR has biological and therapeutic utilization in prostate carcinoma, but its use in EMPD treatment is rarely reported because of few evidence of AR expression in EMPD." (PMID 29082243, 2017). "Exposure of AR-positive prostate cancer cells to supraphysiological concentrations of androgen results in growth inhibition." (PMID 29113300, 2017). "The miRNA-185 suppressesed proliferation, invasion, migration, and tumorigenicity of human prostate cancer cells by targeting the androgen receptor." (PMID 28570571, 2017). "These two target proteins are well‐established molecular chaperone and co‐chaperone proteins, respectively, and are known to be involved in modulating AR signaling during prostate cancer progression and development." (PMID 28252832, 2017). "Most prostate cancer cells express androgen receptor and androgen signaling plays a major role in the proliferation of prostate cancer cells." (PMID 29108248, 2017). "In prostate cancer, CD9 has been identified as a candidate gene involved in androgen-deprived cell proliferation through its interaction with IGSF8, suggesting a role of CD9 itself in AR-mediated prostate cancer progression." (PMID 28881726, 2017). "Impairing AR activity is a targeting for taxol-based chemotherapy during prostate cancer progression." (PMID 29552052, 2017). "Here, we report that YAP1, which is negatively regulated by AR, influences prostate cancer (PCa) cell self-renewal and CRPC development." (PMID 29383141, 2017). "Drugs targeting the androgen receptor (AR) signaling pathway form the backbone of therapy for advanced prostate cancer." (PMID 28891793, 2017). "Deregulation of the AR signaling pathway is crucial for prostate cancer cell proliferation, tumor progression and the development of CRPC." (PMID 27835608, 2016). "There is also a strong evidence supporting a role of GSK3β in prostate cancer where it is involved in promoting androgen receptor function and nuclear translocation." (PMID 27602497, 2016). "Previous studies show that anti-spermatogenesis, anticancer activity and apoptosis in prostate cancer cells were induced by the suppression of AR signaling." (PMID 27399684, 2016). "The phosphoprotein phosphatases are emerging as important androgen receptor (AR) regulators in prostate cancer (PCa)." (PMID 26636645, 2016). "Salinomycin inhibited cell proliferation for AR-expressing LNCaP (castration-sensitive) and C4-2B (castration-resistant) human prostate cancer cells." (PMID 27557496, 2016). "The AR is a necessary contributor to prostate cancer development and is recognized as a meaningful target for prostate cancer prevention and treatment." (PMID 26986969, 2016). "Four bioactive compounds were identified in W. chinensis to inhibit androgen receptor activity in prostate cancer cells and the four active compounds acting together exerted strong synergism (CI= 0.39–0.78)." (PMID 27462269, 2016). "The androgen receptor (AR) is required for prostate development and is also a major driver of prostate cancer pathogenesis." (PMID 26848868, 2016). "Prostate cancer is an androgen receptor (AR)-driven disease and post-translational modification of AR is critical for AR activation." (PMID 27659526, 2016). "To date, 11 different AR-hinge region mutants in prostate cancer tissues or prostate cancer cell lines have been identified." (PMID 27835608, 2016). "During progression of prostate cancer the AR switches from an epithelial anti-proliferative transcription factor to an oncogene." (PMID 27378372, 2016). "In prostate cancer cells, Sam68 functions as a transcriptional co-activator of the androgen receptor (AR), a nuclear hormone receptor driving the onset and progression of prostate cancer." (PMID 27690217, 2016). "In prostate cancer, Killin was shown to decrease prostate-specific antigen levels and suppress androgen-mediated cell growth by inhibiting androgen receptor (AR) transcription." (PMID 27295081, 2016).